RIPOR2 (RHO family interacting cell polarization regulator 2)
Description:
Acts as an inhibitor of the small GTPase RHOA and plays several roles in the regulation of myoblast and hair cell differentiation, lymphocyte T proliferation and neutrophil polarization. Inhibits chemokine-induced T lymphocyte responses, such as cell adhesion, polarization and migration. Involved also in the regulation of neutrophil polarization, chemotaxis and adhesion (By similarity). Required for normal development of inner and outer hair cell stereocilia within the cochlea of the inner ear (By similarity). Plays a role for maintaining the structural organization of the basal domain of stereocilia (By similarity). Involved in mechanosensory hair cell function (By similarity). Required for normal hearing. [Isoform 2]: Acts as an inhibitor of the small GTPase RHOA. Plays a role in fetal mononuclear myoblast differentiation by promoting filopodia and myotube formation. Maintains naive T lymphocytes in a quiescent state.
Synonyms: C6orf32; DIFF48; FAM65B; KIAA0386; PL48; MYONAP; DFNA21; DFNB104; DIFF40
Tractability: Antibody: UniProt places it where antibodies can reach, with medium confidence; its Gene Ontology location is reachable by antibodies, with medium confidence. PROTAC: ubiquitination databases record sites on it.
Safety:
Unwanted effects reported when the protein is acted on. In parentheses: how it was acted on, where the effect was seen, and who reports it.
liver toxicity (source: ClinPGx)
Gene: Protein-coding gene on chromosome 6 (24,803,362 to 25,042,170, reverse strand). Ensembl gene ENSG00000111913.
Subcellular location: Cytoplasm; Cytoplasm, cytoskeleton; Cell projection, filopodium; Cell projection, stereocilium; Cell projection, stereocilium membrane; Apical cell membrane; Cytoplasm (Isoform 1); Cytoplasm (Isoform 2)
Subcellular location (Human Protein Atlas): Cytosol
Pathways (Reactome):
Sensory Perception: Sensory processing of sound by inner hair cells of the cochlea; Sensory processing of sound by outer hair cells of the cochlea
Gene Ontology:
Molecular function: 14-3-3 protein binding; protein binding
Biological process: cellular response to chemokine; negative regulation of cell adhesion; negative regulation of establishment of T cell polarity; negative regulation of Rho guanyl-nucleotide exchange factor activity; negative regulation of Rho protein signal transduction; negative regulation of T cell migration; positive regulation of filopodium assembly; positive regulation of myoblast differentiation; positive regulation of myoblast fusion; sensory perception of sound; negative regulation of protein localization to cell leading edge; positive regulation of neutrophil chemotaxis; positive regulation of neutrophil extravasation; regulation of establishment of cell polarity
Cellular component: cytoplasm; cytoskeleton; cytosol; filopodium; apical plasma membrane; stereocilium; actin-based cell projection; stereocilium membrane
Genetic constraint (gnomAD): Loss-of-function variants: 32 observed, 85.6 expected, observed/expected ratio (o/e) 0.37, 90% interval 0.28 to 0.5. The upper end of that interval is the gene's LOEUF score, 0.5, which puts it in group 2 of 6, group 1 being the genes least tolerant of losing a copy. Missense variants: 861 observed, 1,119.9 expected, observed/expected ratio (o/e) 0.77, 90% interval 0.73 to 0.81. Synonymous variants: 370 observed, 439.71 expected, observed/expected ratio (o/e) 0.84, 90% interval 0.77 to 0.92.
Gene-disease validity (ClinGen):
ClinGen rates the evidence that RIPOR2 causes each of these diseases.
nonsyndromic genetic hearing loss (autosomal recessive): Strong. A disease characterized by hearing loss that is not part of a larger syndrome.
autosomal dominant nonsyndromic hearing loss (autosomal dominant): Limited. Autosomal dominant form of nonsyndromic deafness.
Homologues: Orthologues: chimpanzee RIPOR2 (97% identical), macaque RIPOR2 (94% identical), mouse Ripor2 (88% identical), rabbit RIPOR2 (87% identical), guinea pig RIPOR2 (87% identical), dog RIPOR2 (86% identical), pig RIPOR2 (86% identical), rat Ripor2 (84% identical), tropical clawed frog ripor2 (66% identical), zebrafish ripor2 (54% identical), Caenorhabditis elegans Y37A1A.4 (19% identical). Paralogues in human: RIPOR1 (36% identical), RIPOR3 (34% identical).
Diseases named in the same sentence as RIPOR2 in open-access papers:
RIPOR2 is named in the same sentence as 43 diseases in open-access papers, as found by Europe PMC text mining. Sharing a sentence is not in itself a finding about the gene and the disease. The quoted sentences say what the papers report.
hearing loss (4 papers, 2016 to 2025). "AG-induced hearing loss can be completely or partially prevented by reducing the expression of Ripor2, Gabarap, Lc3β, Pink1, Prkn, or Gabarapl1, as identified in this study." (PMID 39928869, 2025). "RIPOR2, an AG-binding protein previously identified in hair cells, is essential for AG-induced hearing loss, as is the RIPOR2/ GABARAP-mediated autophagy pathway." (PMID 39928869, 2025). "We previously demonstrated that the RIPOR2-mediated autophagy pathway is essential for AG-induced hearing loss." (PMID 39928869, 2025). "Thus, it is critical to identify additional proteins in the RIPOR2/GABARAP signaling pathway to provide additional targets for preventing AG-induced hearing loss." (PMID 39928869, 2025).
cervical cancer (2 papers, 2022). A primary or metastatic malignant neoplasm involving the cervix. "The survival analysis and Kaplan–Meyer curves were performed taking into consideration the high or low expression of PFKFB4 and RIPOR2, according to the median expression levels, in TCGA cervical cancer samples." (PMID 36497200, 2022). "A bioinformatic study revealed that a signature comprising four genes (RIPOR2, DAAM2, SORBS1, CXCL8) was found to be associated with survival in cervical cancer patients." (PMID 36497200, 2022). "Our findings firmly position RIPOR2 as a promising prognostic biomarker in cervical cancer and demonstrate the effect of viral oncoproteins in downregulating RIPOR2 transcriptional variants." (PMID 36497200, 2022). "Clinical specimens of cervical cancer patients at different pathological stages were acquired to further investigate the expression of RIPOR2 protein using IHC and immunofluorescence experiments." (PMID 36091054, 2022). "This suggests the existence of a FOXO1/RIPOR2/RhoA axis mediated by HPV oncoproteins which is affected in cervical cancer and related to an unfavorable clinical outcome." (PMID 36497200, 2022). "Results showed that several transcripts were found to be altered by the E6 and E7 oncoproteins both in a cell model and in cervical cancer, where the decreased expression of RIPOR2 (RHO 2 family-interacting cell polarization regulators) was associated with poor OS, regardless of clinical stage." (PMID 36497200, 2022). "Moreover, when RIPOR2 was overexpressed in SiHa and HeLa CC cell lines, cell viability and migration capacity significantly diminished, suggesting that RIPOR2 is a tumor suppressor gene in cervical cancer." (PMID 36497200, 2022).
asthma (1 paper, 2021). "The proteins encoded by the candidate genes identified in our study are iNOS, SPSB2, and RIPOR2, all of which have functions that could influence the levels of FeNO and the phenotypes of obstructive airway diseases including asthma and COPD." (PMID 34782693, 2021).
Autoimmunity (1 paper, 2021). The occurrence of an immune reaction against the organism's own cells or tissues. "Lastly, we detected the increment of phosphorylated proteins related to T lymphocyte response (e.g., Rho family-interacting cell polarization regulator 2) and the prevention of the cell-intrinsic initiation of autoimmunity (e.g., three-prime repair exonuclease 1)." (PMID 34712240, 2021).
endometrial carcinoma (1 paper, 2022). A malignant tumor arising from the epithelium that lines the cavity of the uterine body. "In most tumor types, RIPOR2 expression is relatively suppressed compared with normal samples, particularly in gynecologic malignancies like endometrial carcinoma." (PMID 36091054, 2022).
glaucoma (1 paper, 2021). Increased pressure in the eyeball due to obstruction of the outflow of aqueous humor. "As for the other two genes nearest to the most significant SNPs, LINC00475 and RIPOR2, there has been no reported association to glaucoma and other eye diseases so far." (PMID 34834521, 2021).
melanoma (1 paper, 2026). A malignant, usually aggressive tumor composed of atypical, neoplastic melanocytes. "We found that RIPOR2 is ectopically expressed in human melanoma and functionally promotes multinucleation in both an animal model and human tumor-derived cells, including melanoma cell lines." (PMID 42100747, 2026). "Similar transcriptional control of RIPOR2 by RAS/ERK is conserved in human melanoma cells." (PMID 42100747, 2026).
Obesity (1 paper, 2025). Accumulation of substantial excess body fat. "Obesity mostly downregulated endothelial-specific DEGs, including Nid1, Sparc, and Ogn, while Ripor2 was the only upregulated endothelial-specific DEG." (PMID 41310161, 2025).
prostate carcinoma (1 paper, 2022). A carcinoma that arises from epithelial cells of the prostate gland. "Tumors derived from prostate cancer cell line PC3, exhibited low expression of RIPOR2, even though a stem-like subpopulation derived from such cell line showed the opposite phenotype." (PMID 36497200, 2022).
schizophrenia (1 paper, 2024). A major psychotic disorder characterized by abnormalities in the perception or expression of reality. "For instance, altered methylation of RIPOR2 was associated with trauma exposure, and POLD4 is linked to schizophrenia risk." (PMID 39020437, 2024).
squamous intraepithelial lesions (1 paper, 2022). "RT-qPCR analysis was performed to determine whether the expression of RIPOR2 was altered in premalignant lesions of the cervix comprising low and high grade squamous intraepithelial lesions (LSIL and HSIL) and normal samples with HPV infection, compared to normal HPV negative samples." (PMID 36497200, 2022).
systemic sclerosis (1 paper, 2025). A chronic disorder, possibly autoimmune, marked by excessive production of collagen which results in hardening and thickening of body tissues. "Analysis of peripheral blood cell samples collected from patients with systemic sclerosis–associated PAH demonstrated revealed the upregulation of RIPOR2 expression." (PMID 40354360, 2025).
uterine carcinosarcoma (1 paper, 2022). A usually aggressive malignant neoplasm arising from the uterine corpus and less often the cervix. "Most of the 24 inhibitory ICPs showed positive correlations with RIPOR2 in most of the 30 cancer types considered here, with the exceptions of brain lower grade glioma (LGG), GBM, PCPG, uterine carcinosarcoma (UCS), and uveal melanoma (UVM)." (PMID 36091054, 2022).
cancer (11 papers, 2010 to 2024). A tumor composed of atypical neoplastic, often pleomorphic cells that invade other tissues. "In the pan-cancer analyses, high RIPOR2 expression was significantly associated with lower TMB in all cancer types, as well as with lower MSI in most tumor types except COAD, PCPG, and READ." (PMID 36091054, 2022). "The results of the univariate Cox proportional hazard regression analysis showed that the expression of RIPOR2 was associated with the OS of cancer patients." (PMID 36091054, 2022). "Other significant genes, including RIPOR2, FAM30A, DLX4 and LAT, are associated with inflammatory/immune processes and various cancer etiologies." (PMID 39020437, 2024). "According to data from The Cancer Genome Atlas 47, the expression of RIPOR2 is downregulated compared to that in normal tissues in the majority of cancer types, especially in uterine corpus endometrial carcinoma and diffuse large B-cell lymphoma." (PMID 35002526, 2022). "HLA-related genes were found to correlate with RIPOR2 expression in the pan-cancer analysis in all cancers apart from LGG, PCPG, UCS, and UVM." (PMID 36091054, 2022). "Based on a comprehensive analysis of 33 cancer types, we concluded that RIPOR2 was generally a protective factor in tumor patients." (PMID 36091054, 2022). "Compared with the results obtained with the same cancer types and methylated RIPOR2 on the top-right, the color block shows the corresponding degree of negative correlation, consistent with the previous results." (PMID 36091054, 2022). "Furthermore, RIPOR2 has also shown links with diversely functioning ICPs in plenty of cancer types, the summation of which tends to enhance immunity." (PMID 36091054, 2022). "Evidence to date suggests that RIPOR2 is a pan-cancer protective factor." (PMID 36091054, 2022). "However, the specific mechanisms by which E6 and E7 downregulate RIPOR2 and their relationship with the development and/or maintenance of cancer is something that deserves further study." (PMID 36497200, 2022). "There is little information on the involvement of RIPOR2 in cancer." (PMID 36497200, 2022). "The study of the expression of RIPOR2 when cancer is diagnosed could have a potential utility as a prognostic biomarker that allows the appropriate decision on surveillance and therapeutic intervention in patients with low risk of survival." (PMID 36497200, 2022). "To determine whether the protective role of RIPOR2 was unique to CC or also existed in other cancers, we conducted a pan-cancer analysis of RIPOR2 expression levels using data from the TCGA." (PMID 36091054, 2022). "With the exceptions of LGG, PCPG, and UVM, strong correlations between RIPOR2 and ICP expression were found in all cancer types." (PMID 36091054, 2022). "The obtained results evidence that RIPOR2 and PFKFB4 are deregulated in CC patients and in C33-E616 and C33-E7 CC cell lines, suggesting that their modulation in this cancer type is partially mediated by E6 and E7 oncoproteins." (PMID 36497200, 2022). "Therefore, the specific roles of each RIPOR2 isoform in physiological and cancer-related are not yet known." (PMID 36497200, 2022).
tumor (8 papers, 2010 to 2026). "Generally, the high RIPOR2 expression group had a lower tumor mutation burden (TMB), higher ESTIMATEScore, and higher proportions of ICPs, and patients in this group responded better to immunotherapy with PD-1 alone or combined with CTLA4." (PMID 36091054, 2022). "Other experimental results showed that RIPOR2 represented an anti-tumor signature in CC, consistent with the results of the bioinformatical analyses." (PMID 36091054, 2022). "Thereafter, we analyzed ICPs to determine the influence of RIPOR2 on the immune environment of tumor patients." (PMID 36091054, 2022). "When we explored potential interactions between RIPOR2 expression and immune scores on a larger scale, a highly positive relationship was discovered in all tumor types." (PMID 36091054, 2022). "As mentioned in the Verification experiments and Transwell, CCK-8, EdU, cell cycle detection, and colony formation assays indicated RIPOR2 as an anti-tumor signature sections, the correlation of RIPOR2 with ICPs was further verified by experiments." (PMID 36091054, 2022). "In agreement, a recent study identified a four gene antitumor signature related to the tumor microenvironment, which included RIPOR2, CCL22, PAMR1, and FBN1 genes." (PMID 36497200, 2022). "According to the results, CC, KIRC, LIHC, PAAD, LUAD, and UCEC patients with the C2 and C3 subtypes—that is, a hotter tumor immune microenvironment and a better response to immunotherapy—had the highest levels of RIPOR2 expression." (PMID 36091054, 2022). "HDAC6, a cytoplasmic deacetylase that accelerates tumor proliferation by triggering deacetylase activity, can bind to phosphorylated RIPOR2 and 14-3-3, forming a tripartite complex and disrupting its original function of forming a mitotic spindle." (PMID 36091054, 2022). "In this sense, our work provides valuable information on the participation of E6 and E7 viral oncoproteins in the regulation of RIPOR2 and its association with clinical evolution in CC, regardless of the tumor microenvironment." (PMID 36497200, 2022). "A series of in vitro experiments, including immunohistochemistry, immunofluorescence, quantitative reverse transcription PCR, transwell assay, CCK8 assay, EdU assay, cell cycle detection, colony formation assay, and Western blotting were performed to validate RIPOR2 as an anti-tumor signature." (PMID 36091054, 2022). "However, the precise role of RIPOR2 in carcinogenesis and tumor development remains to be clarified, and there are still pressing questions left to be explored." (PMID 36091054, 2022). "In comparison, among 16 downregulated genes relative to IQGAP1 under-expression, FAM65B (RIPOR2), PI15, and HDAC9 are downregulated in either iCluster 1, iCluster 2, or both in comparison to the matched non-tumor tissues." (PMID 33498739, 2021).
infection (1 paper, 2022). The state of being infected such as from the introduction of a foreign agent such as serum, vaccine, antigenic substance or organism. "Taken together, these results suggest that RIPOR2 expression is downregulated by HPV-16 E6 and E7 oncoproteins, and it is probably affected from the onset of infection; moreover, our data indicate that decreased expression of RIPOR2 is associated with unfavorable clinical outcome of patients." (PMID 36497200, 2022).
RIPOR2 also shares sentences with these, for which no sentence is quoted: deafness (3 papers); acute myeloid leukemia (2); hematopoietic cancers (2); ischemia (2); bladder urothelial carcinoma (1); breast carcinoma (1); breast invasive carcinoma (1); cardiac hypertrophy (1); cardiovascular diseases (1); colon adenocarcinoma (1); COVID-19 (1); dyslipidemia (1); glioblastoma (1); Hearing impairment (1); heart disease (1); kidney chromophobe (1); leukemia (1); lung adenocarcinoma (1); lung squamous cell carcinoma (1); myocardial infarction (1); nonsyndromic hearing loss (1); prostate adenocarcinoma (1); psychiatric disorder (1); rectum adenocarcinoma (1); type 2 diabetes (1); uterine corpus endometrial carcinoma (1); uveal melanoma (1).